NLRP3 (NLR family pyrin domain containing 3)
Diseases named in the same sentence as NLRP3 in open-access papers (continued):
Sharing a sentence is not in itself a finding about the gene and the disease.
lung diseases (43 papers, 2013 to 2026). "Our study indicated that golden buckwheat as a source of functional food prevents or treats associated lung diseases by modulating the activation of the TLR4/NLRP3 signaling pathway." (PMID 39139945, 2024). "C. phaeocaulis has an anti-inflammatory effect against lung disease associated with excessive activation of the NLRP3 inflammasome/inflammation." (PMID 36677800, 2023). "Consistently, NLRP3-deficient mice are resistant to bacteria-induced lethality, suggesting an important regulator of lung diseases." (PMID 32110933, 2020). "Among individuals with lung diseases caused by members of the M. avium complex, the IL-1β response and NLRP3 inflammasome activation are decreased in PBMCs, monocytes, and macrophages compared with those in healthy controls, indicating increased host susceptibility." (PMID 39511430, 2024). "This is the first study that linked glycine and NLRP3 in lung disorder." (PMID 32110933, 2020). "The sputum of neutrophilic asthma and COPD patients contain elevated levels of extracellular DNA and increased gene expressions of NLRP3 and IL-1β, which correlate with the severity of lung disease." (PMID 40791588, 2025). "Aberrant activation of the NACHT, LRR, and PYD domain‐containing protein 3 (NLRP3) inflammasome contributes to the pathogenesis of fatal and perplexing pulmonary diseases." (PMID 40349158, 2025). "In this study, we mechanistically elucidated the contribution of NLRP3 to silica-induced pulmonary disease." (PMID 40119408, 2025). "Here, we provide mechanistic insights into the role of NLRP3 in driving silica-induced pulmonary disease, further highlighting its potential as a therapeutic target." (PMID 40119408, 2025). "Previous studies have shown that macrophages are a known source of IL-18 which is processed by NLRP3 and contributes to acute lung inflammation in multiple models including cigarette smoke-induced lung disease." (PMID 40777291, 2025). "Here, we review the potential roles of the NLRP3 inflammasome in cardiovascular events, liver damage, pulmonary diseases, and in that wide range of systemic inflammatory syndromes named as a cytokine storm." (PMID 38068879, 2023). "Recently, growing evidence suggests that the NLRP3 inflammasome activation is an important regulator of pyroptosis, which plays various roles in the development of lung diseases." (PMID 36998049, 2023). "More importantly, their study provided a key basis for the ongoing exploration of NLRP3 in the treatment of lung disease." (PMID 36177039, 2022). "Previous studies have revealed that NLRP3 inflammasome activation greatly contributes to cardiovascular, neurological, and lung disease development." (PMID 33663554, 2021). "In conclusion, our results support NLRP3 inflammasome activation and S1P signalling dysregulation in the lung disease elicited by βENaC overexpression, and that both features are associated with mucus obstruction." (PMID 32336954, 2020). "Several studies indicate that NLRP3 inflammasome activation played a key role in PM-induced lung disease, mediated by NF-κB." (PMID 31299012, 2019). "These novel data show the presence and functional activation of the NLRP3 inflammasome by cristobalite silica in human lung epithelial cells that mediates a cadre of lung diseases." (PMID 23402370, 2013). "The activation of the NLRP3 inflammasome is pivotal in the development of various lung diseases." (PMID 41292520, 2025). "Additionally, our results implicating a major role for NLRP3 in driving neutrophil responses are also consistent with studies involving inhibition of the NLRP3 inflammasome or IL-1β itself in other lung disease models." (PMID 40119408, 2025). "The inhibition of NLRP3 inflammasome may be a potential target in the management of fibrosing lung diseases." (PMID 37958797, 2023).
lung diseases (continued). "Together, these findings suggest that, in fibrotic lung diseases of different etiologies, the release of inflammatory factors mediated by the activated NLRP3 inflammasome might be an upstream event driving mucus hypersecretion and cell death." (PMID 37063430, 2023). "In brief, inflammasomes (eg., NLRP3 inflammasome) involve in the pathophysiology of fibrotic lung diseases, studies suggest that NLRP3 inhibition could provide a promising approach against the fibrotic pulmonary process." (PMID 36248872, 2022). "Microorganisms could regulate immune reactions in intestinal and pulmonary tissues through modulating NLRP3 inflammatory bodies, which then affect intestinal and pulmonary disorders." (PMID 35469197, 2022). "Two years later, NLRP3 related to pyroptosis in lung disease was first discerned by scientists in this area, but until now, it had attracted expansive attention in the field of pyroptosis in lung disease." (PMID 36177039, 2022). "This hypothesis is in accordance with evidence that leptin and adiponectin have a role in regulating Th17 and Th2 immune responses in lung diseases, in addition to the expression of pro-inflammatory cytokines and NLRP3 activity, as previously discussed." (PMID 35806353, 2022). "Therefore, it appears that lung diseases are promoted by the secretome from dysfunctional adipose tissue, the altered adipokine profile of which drives NLRP3 inflammasome activation and subsequent production of IL-1β and IL-18." (PMID 35806353, 2022). "Mitochondrial ROS also activate the NLRP3 inflammasome in multiple pulmonary diseases, consistent with an inflammation model that includes our IL18-pathway and HK1 results, ROS-related proinflammatory responses to lung capillary pressure, and evidence of alveolar epithelial injury/SDB interactions." (PMID 34446064, 2021). "Additionally, inflammasomes, consist of caspase-1, apoptosis-associated speck-like protein containing a CARD (ASC) and Nod-like receptor protein 3 (NLRP3), imply a wide variety of chronic or acute inflammations, including lung disease." (PMID 31299012, 2019). "The NLR pyrin domain containing 3 (NLRP3) inflammasome plays a crucial role in lung disease and may have a similar role in upper respiratory tract inflammation." (PMID 25207596, 2014). "Recently, expression of the NLRP3 inflammasome in human airway epithelium following in vivo particulate matter exposure has been shown although its functional significance in lung disease was unknown." (PMID 23402370, 2013). "Our novel data indicate the presence and functional activation of the NLRP3 inflammasome by crystalline silica in human lung epithelial cells, which prolongs an inflammatory signal and affects fibroblast proliferation, mediating a cadre of lung diseases." (PMID 23402370, 2013). "The nucleotide-binding domain leucine-rich repeat and pyrin domain-containing protein-3 (NLRP3) inflammasome plays a central role in inflammatory diseases, including cardiovascular, gastrointestinal, neurodegenerative, autoimmune, hepatic, renal, and pulmonary disorders." (PMID 42260217, 2026). "However, the NLRP3 inflammasome in AMs plays different roles in different lung diseases." (PMID 39420831, 2024). "Moreover, NLRP3-derived cytokines (e.g., IL-1β, IL-18) appear to be the main inducers of a cytokine cascade (involving IL-23, IL-17, IL-26, IL-6, IL-13, and IL-5) that is responsible for the development of pulmonary diseases in morbidly obese subjects." (PMID 35806353, 2022). "Understanding the genetic underpinnings of these sleep-related traits may guide future studies investigating the contribution of sleep disordered breathing to the hypoxemic burden of pulmonary disorders, and identify common mechanisms such as activation of the NLRP3-inflammasome pathway." (PMID 30990817, 2019).
lung diseases (continued). "Some studies have proved that pyroptosis is a new form of programmed cell death dependent on caspase, which is mainly related to NLRP3, and especially ALI is one of the most extensive inflammatory diseases in lung disease research." (PMID 36177039, 2022). "The median ratios of C5AR1, CLEC4A and NLRP3 expression in CD3+ of non-malignant pulmonary diseases were 0.01 [range 0–0.02, p = 0.12], 0.02 [range 0.01–0.08, p = 0.42] and 0.13 [range 0.07–0.22, p = 0.14], respectively." (PMID 36323738, 2022). "The NLRP3 MFI on CD3 positive of early-stage NSCLC patients showed higher expression than non-malignant pulmonary disease whereas C5AR1 and CLEC4A expression levels were not different." (PMID 36323738, 2022). "We speculate that the SAL-mediated regulation of the NLRP3 inflammasome may also improve these lung diseases, which now warrants further investigation in future studies." (PMID 34457117, 2021). "Whether NLRP3 is a transcription or epigenetic factor that affects differentiation and function of epithelial and mesothelial cells to more abnormal cell types culminating in malignant or nonmalignant lung diseases is an unexplored area." (PMID 27650313, 2016).
Autoimmunity (42 papers, 2014 to 2025). The occurrence of an immune reaction against the organism's own cells or tissues. "While a balanced inflammatory response favors inflammation resolution and tissue healing, excessive NLRP3 activation causes detrimental effects and facilitates chronic inflammatory diseases, autoimmunity, and cancer development." (PMID 40219097, 2025). "In neuroinflammation, the NLRP3 inflammasome has an important responsibility for the number of innate immune processes associated with infection neuroinflammation and autoimmunity." (PMID 36211814, 2022). "NLRP3 is an intracellular multiprotein complex responsible for innate immune processes associated with infection, inflammation, and autoimmunity." (PMID 35295780, 2022). "Moreover, vaccine adjuvants can enhance the immune response through activation of the NLR pyrin domain containing 3 (NLRP3) inflammasome, which is part of the innate and adaptive immune system and is linked to a range of autoimmunity." (PMID 40142435, 2025). "The autoimmunity-associated PTPN22 variant promotes NLRP3 activity, caspase-1 activation, and secretion of IL-1β and IL18, which might—at least partially—explain the pro-inflammatory character of this PTPN22 variant in T1D, RA and SLE development." (PMID 32751912, 2020). "Notably, the autoimmunity-associated PTPN22 variant was more effective in NLRP3 dephosphorylation." (PMID 32751912, 2020). "Recently, however, two highly selective inhibitors targeting the NLRP3–ASC–caspase-1–IL-1β/IL-18 axis have emerged, holding significant promise for treating NLRP3-driven diseases, including LN and other autoimmune conditions." (PMID 41357229, 2025). "To date, the role of inflammasomes in autoimmunity have largely focused on NLRP3 and AIM2, but other inflammasome molecules such as NLRP1, and NLR family CARD domain-containing protein 4 (NLRC4) have also been implicated in autoimmunity." (PMID 37081890, 2023). "Together these studies indicate that NLRP3 promotes pathological events driving β cell autoimmunity." (PMID 37081890, 2023). "The NLRP3 inflammasome is a multi-protein complex participating in diverse innate immune processes such as infection, inflammation, and autoimmunity." (PMID 37371374, 2023). "Pharmacological or genetic inhibition of NLRP3 and caspase-1 improved renal function and suppressed autoimmunity in LN." (PMID 34867948, 2021). "The activation of NLRP3 inflammasome-IL-1β pathway in keratinocytes contributes to the melanocyte death via autoimmunity-dependent manner in vitiligo." (PMID 32754591, 2020). "In the present study, we found elevated levels of NLRP3 inflammasome and inflammatory cytokines (IL-1β, IL-6, IL-17) in CSF in patients with autoimmune GFAP astrocytopathy." (PMID 31681133, 2019). "The presence of autoimmunity associated PTPN22 variant in mice (PTPN22-619W) resulted in dephosphorylation and activation of NLRP3, while loss of PTPN22 resulted in decreased NLRP3 mediated IL-1β secretion." (PMID 30915320, 2019). "This indicated that one of the functions of NLRP3 is the regulation of Th17 responses that can markedly affect T cell-mediated autoimmunity." (PMID 30140708, 2018). "Inefficient clearance of cellular debris in SLE results in the elevation of reactive oxygen species and mediates NLRP3 activation, and the accumulation of cytosolic self-DNA in autoimmunity triggers AIM2 inflammasome-mediated IL-1β production." (PMID 28266599, 2017). "The NLRP3 inflammasome exists in the pathogenesis of a variety of diseases, including genetically-inherited autoimmune conditions and many chronic diseases." (PMID 27973457, 2016). "Repurposing sulphonylureas and their derivatives to target NLRP3 may act as adjunct therapeutics for autoimmune conditions." (PMID 40686254, 2025).
Autoimmunity (continued). "Although NLRP3 inflammasome activation is essential for host defense and tissue repair, its dysregulation precipitates a spectrum of acute and chronic inflammatory diseases, including autoimmunity, metabolic syndromes, and respiratory pathologies." (PMID 41155878, 2025). "A comprehensive review and critical analysis of published research sourced from PubMed and Google Scholar was undertaken to evaluate the targeted activity and efficacy of the sulphonylureas against the NLRP3 inflammasome, particularly in relation to a subset of related autoimmune conditions." (PMID 40686254, 2025). "Immune system diseases further amplify cardiovascular injury: population-level data link autoimmunity to heightened CVD risk, while AIM2- and NLRP3-dependent axes accelerate atherogenesis and destabilize plaques, particularly in clonal hematopoiesis and after acute infectious or ischemic insults." (PMID 41488670, 2025). "NLRP3 has been the most extensively studied inflammasome, in general and in autoimmunity." (PMID 37081890, 2023). "Our observations illustrate that IL-17A promotes IL-1β production from orbital fibroblasts via the NLRP3 inflammasome in GO, and cytokines subsequently released may induce more inflammation and autoimmunity." (PMID 37109536, 2023). "While the etiology and pathophysiology of IC remain unclear, it may involve autoimmunity in light of the significant role played by the NLRP3 inflammasome." (PMID 35720309, 2022). "MSC inhibit the NLRP3 inflammasome activation and IL-1β release by DCs, which might prevent autoimmunity induction." (PMID 29434214, 2018). "Complications of autoimmunity induced by aberrant NLRP3 inflammasome activation have a great degree of mechanistic crossover with alloimmune injury in solid organ transplant, and stratagems to neutralize NLRP3 inflammasome activation may prove beneficial in solid organ transplant management." (PMID 34639062, 2021). "The activation of the inflammasome has been proposed as a mechanism of autoimmunity in MS patients, a hypothesis that is supported by rare variants in inflammasome components NLRP1, NLRP3, NLRP5 and NLRP9 which were identified in MS families, or found to correlate with disease course and severity." (PMID 31170158, 2019). "In autoimmune POI models (for example, IFN-γ injury and ZP3 immunization), aberrant NF-κB signaling primes NLRP3–caspase-1–GSDMD-mediated granulosa-cell pyroptosis." (PMID 41465179, 2025). "Additionally, inflammasomes play a vital role in the development and progression of autoimmunity, inflammation and metabolic disease, and many SNPs in inflammasome-associated genes, including NLRP1, NLRP3, NLRP12 and CARD8, are involved in and associated with patient susceptibility to T1DM." (PMID 34867336, 2021). "Future work is needed to test these ideas, especially since in the B6/lpr autoimmune model, NLRP3 and ASC can play a protective role against autoimmunity, which is the opposite of what we predict here." (PMID 28533778, 2017). "This suggested that active NLRP3 in patients with AIT might partially regulate Th1 and Th17 differentiation to mediate AIT autoimmunity." (PMID 39621557, 2025). "Direct NLRP3 inhibitors, caspase-1 inhibitors, and purinergic (P2X7) antagonists are newer options for selected inflammasome-driven disease, and upstream TLR antagonists and cGAS–STING pathway modulators are in development for treating sterile inflammation and autoimmunity." (PMID 41440484, 2025). "Nevertheless, whether keratinocyte-derived IL-1β damages melanocytes in an autoimmunity-independent way and whether TR could ameliorate the melanocyte damage via inhibiting the NLRP3-IL-1β pathway in keratinocyte still are not clear." (PMID 32754591, 2020).
Autoimmunity (continued). "On the one hand, it might be the effect of the stimulation concentration; on the other hand, it might indicate that PBMCs without a disease background only change the expression level of NLRP3, which is not sufficient to alter the immune cell differentiation balance to regulate autoimmunity." (PMID 39621557, 2025).